APOE (apolipoprotein E)
Diseases named in the same sentence as APOE in open-access papers (continued):
Sharing a sentence is not in itself a finding about the gene and the disease.
Hypertension (continued). "The effects of apolipoprotein E on the brain age index values were more pronounced in individuals with hypertension in the Korean group alone (ɛ4 carriers × hypertension, β = 0.777, P = 0.038)." (PMID 39007039, 2024). "The mediation effects remained significant after additional adjustments for APOE ε4 status, hypertension status, smoking history, VO2max, and further vitamin B12 levels (Effect = −0.020, SE = 0.012, 95% CI [−0.048; −0.003])." (PMID 39170895, 2024). "In the univariate analyses, we found hypertension, anticoagulant use, APOE genotype, presence of cSS, and previous lobar ICH were associated with lobar ICH development (p < 0.2)." (PMID 36635759, 2023). "Apart from older age, the strongest clinical predictors were current diagnosis of hypertension, lower baseline MoCA scores, APOE ε4 status, and to a lesser extent, higher baseline MDS-UPDRS III scores." (PMID 36926634, 2023). "The exact cellular source and isoform of mTBI-induced ApoE in hypertension should be established by future studies." (PMID 38073626, 2023). "Among UK-ADRC cases (n = 92) with clinical, neuropathological, and genetic information, the majority of cases had hypertension (59.0%), hypercholesterolemia (58.4%), and the APOE ɛ3/ɛ3 genotype (64.6%)." (PMID 37641147, 2023). "More recently, adipose-tissue specific knockout of Bone Morphogenetic Protein 4 (BMP4) in apolipoprotein E (ApoE) knockout mice gave rise to high levels of angiotensinogen, angiotensin II, and ROS, resulting in hypertension development." (PMID 37190105, 2023). "In multivariate analyses, age, current diagnosis of hypertension, baseline MoCA scores, Movement disorder society Unified PD Rating Scale part III (MDS-UPDRS III) scores, and APOE status were associated with the development of CI." (PMID 36926634, 2023). "In multivariate analyses, CI was associated with the age of onset, current diagnosis of hypertension, baseline MoCA scores, MDS-UPDRS III scores, and APOE status." (PMID 36926634, 2023). "Age, sex, education, BMI, APOE E4 status, diet, physical activity, hypertension and intellectual scores, QUICKI scores, lab measures." (PMID 35571887, 2022). "In the meanwhile, deficiency of BMP4 also aggravates Ang II (angiotensin II) -induced hypertension and vascular remodeling in ApoE–/– mice." (PMID 36457800, 2022). "An animal study has shown that the pathogenesis of hypertension in ApoE(−/−)/Cyp1b1(+/+) mice fed a high-fat diet is most likely due to oxidative stress caused by CYP1B1, as well as increased plasma lipid levels." (PMID 36158751, 2022). "Years of education, hypertension, high levels of Hcy, elevated WMV, WMH, LI, and Fazekas scores, and carrying the APOE-ε4 gene are risk factors for VCIND in stroke patients." (PMID 35317127, 2022). "This study is the first to investigate the relationship between both APOE and MTHFR gene polymorphisms and hypertension in the Hakka people." (PMID 36158751, 2022). "ApoE−/− mice had normal blood pressure levels, and ApoE/NOS3−/− mice exhibited hypertension-induced pathological changes." (PMID 36360235, 2022). "In this study, the association of APOE rs429358, rs7412, and MTHFR rs1801133 genetic polymorphisms with hypertension was analyzed in a Hakka population." (PMID 36158751, 2022). "In the present study, the relationship between APOE and MTHFR polymorphisms and hypertension was analyzed in a Hakka population." (PMID 36158751, 2022). "It is associated with multiple factors such as the polymorphism of apolipoprotein E (APOE) gene, presenting the APOε4 allele, hyperlipidemia, hypertension, type II diabetes, and coronary disease." (PMID 35443732, 2022). "Knockout of BMP4 either in adipose tissue or specifically in BAT aggravates high-fat diet (HFD, 40% fat)-induced hypertension and endothelial dysfunction in ApoE–/– mice." (PMID 36457800, 2022).
Hypertension (continued). "miR-663 has been reported to target renin (REN) and apolipoprotein E (APOE) mRNAs and a decrease in miR-663 has been associated with an increase in renin mRNA in patients with hypertension." (PMID 36712680, 2022). "Cognitively, APOE ε4 carriers with hypertension mainly showed decreased execution functions, memory and language in the large cohort study." (PMID 35624902, 2022). "Patients with hypertension who were APOE rs429358C/C homozygous had higher TG, TC, LDL-C, and Apo-B levels, whereas patients with the T/T genotype had higher HDL-C levels." (PMID 36158751, 2022). "Patients with hypertension who were APOE rs7412T/T homozygous had higher TG and TC levels and lower LDL-C and Apo-B levels." (PMID 36158751, 2022). "After correction for age at MRI, sex, APOE ε4 status, and controlled hypertension, HR (P = 0.023), MAP (P = 0.006), SBP (P = 0.012), and DBP (P = 0.008) at rest remained positively associated with WMH fraction." (PMID 35898329, 2022). "There is a significantly higher subcortical white matter lesion volume in APOE ε4 carriers with hypertension than in non-ε4 carriers." (PMID 35624902, 2022). "The purpose of this study was to look at the relationship between apolipoprotein E (APOE) and methylenetetrahydrofolate reductase (MTHFR) polymorphisms and essential hypertension in the Hakka population." (PMID 36158751, 2022). "Although rs439401 is less interrogated compared to other APOE SNPs, but we found a study linking the SNP with high blood pressure, and another linking SNP’s allelic variation to poor metabolic profile (obesity, insulin resistance and high triglyceride level." (PMID 36088317, 2022). "For females, variables or nodes with the highest degrees of betweenness included ApoE and hypertension." (PMID 34267647, 2021). "First, older apolipoprotein E-knockout mice, a longer experimental period, and a higher-fat diet should have been used to investigate hypertension and cardiac fibrosis during cardiac hypertrophy." (PMID 34394711, 2021). "There were differences in cigarette smoking, education, dental status, hypertension, hyperlipidaemia and APOE results between the two crowds in different fluorine drinking water areas." (PMID 34886821, 2021). "Association of APOB, APOE, and MTHFR polymorphisms with higher lipid levels and the risk of developing hypertension and cardiovascular diseases have been described." (PMID 34616421, 2021). "Homozygous APOE ε4 carriers with hypertension had significantly higher levels of CSF tau and ptau-181 compared to individuals of the same genotype, but no hypertension." (PMID 34867762, 2021). "The results showed that the effects of APOE ε4, hypertension, low education, and obesity on cognitive trajectories were significantly different in EOAD vs. LOAD patients." (PMID 34127075, 2021). "Several factors can contribute to the disease, including aging, mutation on genes such as the apolipoprotein E (APOE) ε4 gene, Presenilin 1 (PSEN 1) and Presenilin 2 (PSEN 2) as well as risk factors such as obesity and hypertension." (PMID 34577171, 2021). "It was found that the link between hypertension and levels of CSF tau and p-tau 181 was modulated by APOE genotype but differed between individuals depending on the characteristics of the genotype present." (PMID 34867762, 2021). "In women, APOE e4+/+ status (β = − 0.78, 95% CI − 1.56 to − 0.01, p = 0.05), stroke (β = − 0.092, 95% CI − 1.83 to − 0.01, p = 0.05) and hypertension (β = − 0.48, 95% CI 0.87 to − 0.09, p = 0.02) were associated with memory decline." (PMID 33833259, 2021). "In conclusion, ApoE e2e3 was associated with reduced total and LDL cholesterol, and reduced risks of CAD and hypertension." (PMID 32511104, 2020). "Clinical manifestations of LPG patients include mild nephrotic problem initially but later progress to nephrotic syndrome with elevated levels of serum apolipoprotein E (apoE), hyperlipidemia, hypertension and microscopic hematuria." (PMID 32441489, 2020).
Hypertension (continued). "Hypertension, WHR and APOE ε4 homozygosity emerge as the dominant risk factors in terms of the spatial extent of the probability of WMHs and the number of significant voxels after controlling for head size, age, sex and their interaction." (PMID 32971464, 2020). "Cardiac hypertrophy has been seen in aged ApoE KO mice fed with high-fat diet due to increased afterload from hypertension." (PMID 31575906, 2019). "This interaction of APOE e4 and untreated hypertension was also consistently observed for the global score." (PMID 31697783, 2019). "Unmodifiable AD-related factors such as sex, APOE-ε2, and maternal family history were associated with distinct regional patterns of WMH that persisted after adjustment for age and hypertension status." (PMID 30678723, 2019). "Aged ApoE knockout mice fed high-fat diet for 6 weeks developed hypertension, and myocardial hypertrophy with impaired cardiac function." (PMID 31575906, 2019). "Age-adjusted characteristics of women at baselinea according to physician-diagnosed hypertension and APOE e4 genotype status (n = 8300)." (PMID 31697783, 2019). "Studies of the interaction between genetic factors (APOE e4) and hypertension on cognitive function have been conducted." (PMID 31697783, 2019). "For the cross-sectional cohort, patients with AD had significantly higher mean age, lower level of education, and more frequent apolipoprotein E (APOE) ε4 allele and hypertension than CN individuals." (PMID 29515131, 2018). "We used Rgs1−/− mice on an ApoE−/− background, as hyperlipidemia is a common co-morbidity with hypertension." (PMID 29654907, 2018). "When introduced in model B, disease variables including APOE*ε4 and hypertension and CVD history greatly reduced the effect of cognitive function on HbA1c slope." (PMID 29860628, 2018). "Hypertension and CAA are the most common causes of ICH, and CAA is known to be associated with apolipoprotein E (ApoE)-ε4 genotype." (PMID 28555127, 2017). "APOE ɛ4 remained significant (OR: 2.37; 95% CI: 1.37, 4.07), as did hypertension (OR: 0.55; 95% CI: 0.32, 0.93)." (PMID 28578665, 2017). "Model 1 is unadjusted, Model 2 is adjusted for alcohol intake, smoking status, APOE genotype (rs429358 and rs7412), sex, education, BMI, depression, hypertension, diabetes type 1 and 2, history of cardiovascular diseases, and physical activity." (PMID 28647580, 2017). "After controlling for age, other significant risk factors were depressed mood, smoking, alcohol use, and history of hypertension, CVD and cancer, and being a carrier of the APOE-ε4 allele." (PMID 28983317, 2017). "Although a controversy remains concerning the development of hypertension in ApoE-KO mice, we analyzed the effects of BM-573 on blood pressure in young ApoE-KO mice through direct arterial pressure measurements by telemetric recordings." (PMID 27019366, 2016). "Compared with controls, LOAD patients showed a higher number of females (64% vs. 53%, respectively) and APOE ε4 carriers (39% vs. 15%, respectively), less hypertension rate (38% vs. 53%, respectively) and hypercholesterolemia (18% vs. 31%, respectively)." (PMID 27249957, 2016). "Because hypertension is induced by Ang II, we also examined this parameter in the control and treated apoE-/- mice." (PMID 25876091, 2015). "In this study, we report that infusion of AngII into apoE (-/-) mice modified T cell cytokine profile and induced hypertension." (PMID 26121471, 2015). "In contrast to Western diet fed WT mice, ApoE −/− mice develop cardiovascular disease (hypertension)." (PMID 26167199, 2014). "Treatment of WD-fed ApoE-/- mice with GGDGT reduced hypertension by protecting the endothelium-dependent vasorelaxation response." (PMID 25416139, 2014). "Age, gender, ethnicity, education, caloric intake, BMI, family history of AD, Apolipoprotein E (APOE) genotype, presence of hypertension and insulin resistance were examined as confounds." (PMID 25599008, 2014).
Hypertension (continued). "A review of predictors of cognitive change identified education, hypertension, health, cardiovascular disease, and the APOE e4 gene as significant predictors; however, effects of physical activity on cognitive change were inconclusive." (PMID 24901793, 2014). "After controlling for age, education, BMI, and presence of hypertension, they found a significant exercise group by APOE status interaction." (PMID 24961307, 2013). "In our study, treatment with DYSGT in WTD-fed ApoE KO mice reduced hypertension as well as insulin resistance." (PMID 24062791, 2013). "These additional events provide increased power to detect potential risks for transition including age, gender, education, APOE-4, family history of dementing illness, and baseline hypertension." (PMID 22536535, 2012). "In our and other laboratories, this issue has been addressed by activating the renin-angiotensin system through partial clipping (stenosis) of the left renal artery (known as two kidney-one clip, or 2K1C, hypertension) in young apoE-/- mice." (PMID 22330242, 2012). "Augmented Nox2 expression has been linked to aortic and cerebral vascular dysfunction in male apolipoprotein E-null (ApoE−/−) mice maintained on a HF (21%) diet from 5 weeks of age, and inhibition of Nox2 reduces the hypertension." (PMID 23227196, 2012). "Long-term recordings of HR and BP show evidence that apoE-/- mice exhibit hypertension and tachycardia and abolition of their circadian cycles, primarily when under the influence of aging and a Western-type diet." (PMID 22330242, 2012). "The association between classical CVD risk phenotypes (hypertension, obesity and lipid status) and the four widely investigated CVD candidate gene polymorphisms is tested: ACE I/D, APOE (ε2, ε3, ε4), eNOS-VNTR and LEP G2548A." (PMID 21244662, 2011). "Diabetes, hypertension,previous stroke, and APOE 4 genotype independently contributed to cognitivedecline in late middle age and early elderly years." (PMID 29213654, 2010). "Similarly, for the model that additionally adjusted for hypertension, hyperlipidemia, low eGFR, and statin use, the odds of IHD were 2.38 times greater (95 % CI: 0.94–6.89) for each additional APOE ε4 allele." (PMID 41282305, 2025). "In the SEM analysis, we posited that cardiometabolic measures (hypertension, type 2 diabetes, hypercholesterolemia), BMI and Aβ status are influenced by age, sex, APOE ε4 status, and region of residence, which may, in turn, influence CMHs prevalence." (PMID 40832697, 2025). "Additionally, the observed cost differences across biomarker-defined subgroups, particularly those related to APOE, Aß status, or hypertension, highlight the complex interplay between biological and clinical factors in shaping healthcare utilization and costs." (PMID 40571933, 2025). "For example, a meta-analysis reported that APOE ε2 and APOE ε4 were associated with lobar ICH risk in White but not Black or Hispanic participants; however, after controlling for hypertension, APOE ε4 was associated with lobar ICH risk in Hispanic but not Black participants." (PMID 41035821, 2025). "In our study, CD34-CreER;Rosa26-tdTomato&ApoE-/- mice with angiotensin II-induced hypertension were used to observe the unique functions of CD34+ cells in hyperlipidemia and hypertension-induced cardiac remodeling through single-cell RNA sequencing (scRNA-seq) and genetic lineage tracing." (PMID 39198543, 2024). "Our research indicated that even when accounting for factors such as AF, Hypertension, SBP, Stroke, Type 2 diabetes, Triglycerides, LDL, HDL, apolipoprotein A1 levels, apolipoprotein B levels, and apolipoprotein E levels, migraine continues to elevate the risk of AD." (PMID 38903170, 2024). "Brain age gap in middle-age was associated with hypertension (P = 0.007) and alcohol intake (P = 0.008) but not apolipoprotein E epsilon 4 allele (P = 0.14), amyloid centiloids (P = 0.39) or cognitive performance (P = 0.74)." (PMID 39605972, 2024).
Hypertension (continued). "This association was not influenced by demographic information, APOE ε4 status, baseline cognitive status, or previous disease status including hypertension and smoking, and AD CSF core features." (PMID 39328245, 2024). "Third, the relationship between APOE gene polymorphisms and the risk of coronary atherosclerosis in patients with different grades of hypertension has been not analyzed in this study." (PMID 39261765, 2024). "Further, we were not able to control for apolipoprotein E (APOE) ε4 allele carriership and information on treatments (eg, for managing dyslipidemia or hypertension) was not always available." (PMID 38676366, 2024). "In univariate analysis, the age of onset, sex, current diagnosis of hypertension, baseline MoCA scores, UPSIT scores, SCOPA-AUT gastrointestinal domain scores, RBDSQ-q6 scores, MDS-UPDRS III scores, the Hoehn and Yahr stage, and APOE status were associated with CI." (PMID 36926634, 2023). "One potential explanation is that hypertension and APOE ε4 gene expression may affect brain function and structure through different pathways." (PMID 38062190, 2023). "For categorical variables, all values should be interpreted as comparison to: male sex, CN diagnostic group, ApoE E4 non-carrier group and no hypertension group." (PMID 36970283, 2023). "Models with other temporal interactions (diagnostic group, age, ApoE, education, hypertension, BMI, and GDS) did not dissipate the association, suggesting that this sex difference was not (fully) mediated by the effect of other temporal associations." (PMID 36970283, 2023). "Analyses using propensity score matching accounting for hypertension burden showed a modest association of APOE ε4 with lobar ICH risk among Hispanics but not in black participants." (PMID 37168667, 2023). "This suggests that the APOE ε4 gene may exacerbate the impact of hypertension on cognitive function." (PMID 38062190, 2023). "The effect of APOE was thus examined as a random factor in the univariate generalized linear analysis, with age, gender, the presence of hypertension or dyslipidemia, and L-HDL-C% (the most strongly correlated of the examined lipids) contemplated as covariates." (PMID 36768512, 2023). "Interestingly, both hypertension and APOE ε4 influence the WM tracts, especially in the frontal and subcortical regions." (PMID 35624902, 2022). "The pathophysiology of hypertension may be influenced by functional changes in ApoE, which regulates lipoprotein metabolism, as well as sympathetic nervous excitement manifested by elevated plasma catecholamine levels." (PMID 36158751, 2022). "The APOE rs429358 polymorphism in these genetic modes (gender-, age-, smoking-, and drinking-adjusted) was not a significant risk factor for hypertension." (PMID 36158751, 2022). "The median and mean ages of DLB patients, both age at visit and onset, were older, and DLB patients had higher proportions of hypertension (32.6% vs. 17.2%, p = 0.015) and DM (23.9% vs. 10.8%, p = 0.018), as well as were more APOE ε4 carriers (57.6% vs. 12.9%, p < 0.001) than PDD patients." (PMID 36123648, 2022). "Third, the relationship between only the common SNPs of APOE and MTHFR and hypertension was analyzed, but other polymorphisms of APOE and MTHFR may also influence the development of hypertension." (PMID 36158751, 2022). "Compared to those excluded due to not having repeated CVLT measures, women with repeated CVLT measures were more likely to be younger, have higher education and income, and currently drink alcohol, but less likely to report having hypertension and carry the ApoE e4 genotype." (PMID 35113870, 2022).